EGFR (epidermal growth factor receptor)
Diseases named in the same sentence as EGFR in open-access papers (continued):
Sharing a sentence is not in itself a finding about the gene and the disease.
tumor (continued). "The most frequently mutated genes across all tumor types included KRAS (30 patients), PIK3CA (16 patients), BRAF (6 patients), EGFR (5 patients), NRAS (4 patients), and ERBB2 (3 patients)." (PMID 29854313, 2018). "EGFR (ErbB1) is a receptor tyrosine kinase (RTK) that is often mutated and overexpressed in many types of solid tumors, resulting in tumor growth." (PMID 29562664, 2018). "The use of selective inhibitors such as anti-EGFR or anti-ALK therapies in patients can lead to tumor shrinkage and prolonged survival." (PMID 29890761, 2018). "Since it became apparent that KRAS mutations are not only prognostic but also predictive of response to anti-EGFR therapy, numerous studies have investigated intra- and inter-tumor heterogeneity for KRAS status." (PMID 30234115, 2018). "In GBMs, the initial driving event is thought to be high copy number amplification of the EGFR gene, present in tumor cells as double minutes (extrachromosomal circular DNA fragments) with levels ranging from >5 to more than 100 copies per cell." (PMID 30518123, 2018). "Aberrant EGFR activation in tumor cells can result from increased transcriptional expression and/or gene amplification or activating mutation." (PMID 30081606, 2018). "Recently, the first ctDNA screening test (cobas® EGFR Mutation Test v2, Roche, Switzerland) for molecular analysis of ctDNA in metastatic NSCLC patients in whom mutation screening was impossible in tumor tissue was approved by the FDA." (PMID 29441349, 2018). "All these studies collected matched blood and tumor tissue from patients with histologically-confirmed diagnosis of advanced NSCLC who progressed to prior EGFR-TKI." (PMID 30190486, 2018). "Our results support a model that the EGFR facilitates tumor malignancy by reducing ETV6, which enhances TWIST1 activities." (PMID 29455655, 2018). "Further, the identification of nuclear EGFR complexes in various tumor types suggests that downstream target genes of nuclear EGFR, as transcription factor, are distinct and cell type specific." (PMID 29449326, 2018). "To demonstrate the potential therapeutic benefit of the DVD-Ig format, we chose a bispecific antibody targeting EGFR to test efficacy in a mouse tumor xenograft model." (PMID 28585177, 2018). "We assessed for the first time in EOC cells that PLEKHA7 induces changes in the asset of E-cadherin-containing cell-cell contacts thus inhibiting E-cadherin/EGFR crosstalk and leading to a less aggressive tumor phenotype." (PMID 29996940, 2018). "Proliferation and tumor growth in xenograft model were performed to evaluate the drug sensitivities of EGFR-tyrosine kinase inhibitors (TKIs)." (PMID 29455655, 2018). "As the internalization of affibody molecules after binding to EGFR is slow, the majority of the specifically bound tracer remains on the cell surface of both tumor cells and hepatocytes." (PMID 30231504, 2018). "AFs of concordant point mutations and indels in EGFR, KRAS, and PIK3CA ranged from 0.3 to 52% in tumor tissue DNA and in plasma cfDNA from 0.2 11.6%." (PMID 29441349, 2018). "Here, we employed an autochthonous c‐Fos‐dependent OS mouse model (H2‐c‐fosLTR) and human OS tumor biopsies for preclinical studies aimed at identifying novel biomarkers and therapeutic benefits of anti‐EGFR therapies." (PMID 30361264, 2018). "We established a novel human tumour–skin co-culture assay to evaluate anti-EGFR antibody effects on both tumour and human skin tissue, the latter being the site of target-mediated adverse effects in patients." (PMID 30301942, 2018). "In GBM patients with amplification of the EGFR gene, the overall prevalence of EGFRvIII is 50–60%15 and has been reported to contribute to tumor stem cell maintenance." (PMID 29377763, 2018).
tumor (continued). "Taken together, we report the screening and identification of HLA-A*2402-restricted epitopes and evaluated the potential of peptide 327 as an inhibitor of the Eps8/EGFR complex in vitro and in tumor-bearing mice." (PMID 29515106, 2018). "For the analysis of EGFR gene copy-number variation, we used quantitative droplet-digital PCR on DNA extracted from microdissected tumor cells." (PMID 29492209, 2018). "When using EVs that originated from parental cell lines with overexpression of EGFR and EGFRvIII (i.e., Gli36), our data showed a higher enrichment of tumor-specific EVs when Cetuximab alone was used (20 μg mL−1 used on-chip)." (PMID 29330365, 2018). "In contrast, the late-stage effects of EGFR activation on tumor promotion likely stem from the direct activation of proliferative, migratory, and survival pathways in the tumor cells themselves." (PMID 29904166, 2018). "Both antibody and peptide EGFR-targeting vectors have been progressed into Phase I clinical trials, and showed the capacity to home to the tumor." (PMID 30233374, 2018). "EGFR on tumor cells has been established as a factor predicting treatment resistance and poor prognosis, making anti-EGFR a potential and promising treatment strategy." (PMID 29580204, 2018). "On the contrary, RAS wild‐type tumor with a mesenchymal phenotype seems to be intrinsically resistant to anti‐EGFR agents in preclinical models." (PMID 29658188, 2018). "Like HD-PTP, UBAP1 is important for EGFR degradation and α5β1 integrin turnover, and is a candidate tumour suppressor." (PMID 30190330, 2018). "Epidermal growth factor receptor (EGFR) is a receptor found on both normal and tumor cells that is important for cell growth." (PMID 29922160, 2018). "The two treatment-naïve cases with the highest level (log2 ratio >4.0) focal EGFR amplicons had uniform high staining of PD-L1 on the tumor cell surfaces." (PMID 29996881, 2018). "Specific areas of interest include the effect of anti-EGFR agents in the chemotherapy induction phase and pre-randomisation (six patients in total) and the role of primary tumour location as a marker of response to treatment." (PMID 29254887, 2018). "The fact indicated EGFR-TKIs suppress tumor growth through its tyrosine kinase inhibitor and is highly effective as evidenced by the high DCR of over 80–90%." (PMID 30055587, 2018). "Taken together, these results indicate that CAR T cells specifically recognize EGFR-positive tumor cells and enhance tumor cell apoptosis." (PMID 29685162, 2018). "Together, these in vivo findings were in agreement with our in vitro results and indicated that Lycorine therapeutically suppressed GBM tumor growth in intracranially orthotopic xenograft model through suppressing the EGFR signaling pathway." (PMID 30016965, 2018). "Tumor biopsies were taken prior to the start of neoadjuvant therapy for expression of EGFR, Her-2-Neu, and GADD45 by immunohistochemistry and for HPV by PCR." (PMID 29386013, 2018). "PTPRK can directly dephosphorylate EGFR during both basal- and ligand-stimulated EGFR phosphorylation, and it can contribute to tumor suppression through its negative regulation of EGFR signaling." (PMID 30208623, 2018). "Activation of downstream pathways of RTKs, such as ERBB2, EGFR, and IGF1R, has been proven to be related to tumor cell anoikis resistance, and IBC cells have been associated with more evasion of anoikis which is consistent with our findings." (PMID 30086764, 2018). "We showed that miR-3140 suppressed in vitro tumor cell growth by directly reducing EGFR expression in NCI-H1975 cells, which are EGFR-TKI resistant due to EGFR L858R/T790M double mutations." (PMID 29540837, 2018). "On univariate analysis, only EGFR staining at >50% of tumour cells (HR = 3.57, p = 0.038) and CD44 staining at 3+ intensity (HR = 7.99, p = 0.004) were associated with a poorer overall survival." (PMID 29731973, 2018).
tumor (continued). "Here, we describe the internalization mechanisms by which PGE2 regulates EGFR nuclear translocation and affects tumor gene expression and cancer cell proliferation." (PMID 29599917, 2018). "Recently, anti-EGFR agents, including EGFR tyrosine kinase inhibitors and anti-EGFR antibodies, have been effectively used for tumor treatment." (PMID 29682203, 2018). "The first-generation EGFR tyrosine kinase inhibitor (EGFR-TKI) reversibly binds to the ATP-binding pocket of EGFR, resulting in EGFR signaling inhibition and tumor growth suppression." (PMID 30420490, 2018). "The targeting of epidermal growth factor receptor (EGFR), a cell-surface receptor in the ErbB family, has shown anti-tumour activity and has been seen as a promising therapy in oncology." (PMID 30054711, 2018). "The expression level of four miRNAs: miR-133b, -146a, -7 and -21 which target EGFR was investigated by real-time PCR in tumor specimens from NSCLC patients treated with erlotinib administered as the second or third line." (PMID 29689091, 2018). "Inhibition of EGFR tyrosine kinase activity can prevent tumor growth, metastasis and angiogenesis, and increase tumor cell apoptosis." (PMID 29455664, 2018). "In this study, our findings suggest that miR-3140 suppresses tumor cell growth not only in various cancer cells, but also in EGFR-TKIs-resistant cells and JQ1-resistant cells." (PMID 29540837, 2018). "In terms of the comparison of EGFR T790M testing using cfDNA and tumor tissue, our method demonstrated a 78.6% concordance, which is above the average in previous studies comparing several methods." (PMID 30444875, 2018). "UniCAR 28/ζ-modified T cells are able to efficiently eradicate tumor cells in the presence of the α-EGFR-EGFR TM." (PMID 29876011, 2018). "Using EVs, an antitumor miRNA (let-7a miRNA) was delivered to EGFR-expressing xenograft breast cancer cells in mice; this delivery system efficiently inhibited the tumor growth." (PMID 29541030, 2018). "Tumor stroma also induces cancer stem cell phenotype by interacting with EGFR that is present on cancer cells through different downstream molecular players." (PMID 29455658, 2018). "For instances, non-small cell lung cancer patients who initially well responded to EGFR inhibitors, erlotinib or gefitinib had host adaptive response and tumor growth within 6–12 months." (PMID 29455663, 2018). "EGFR was considered positive when ≥1% of the tumor cells had membranous staining above the background level, while the intensity of the EGFR reactivity was scored as +1 (mild), +2 (moderate) and +3 (strong)." (PMID 30521571, 2018). "We previously created a bispecific, de-immunized immunotoxin (EGFATFKDEL) that targets EGFR on tumor cells and uPAR, both on tumor cells and their neovasculature." (PMID 29552283, 2018). "Metastatic CRC patients with BRAF mutant tumours are characterised by poor response rates to the anti-EGFR monoclonal antibodies (moAb) panitumumab and cetuximab and poor prognosis, with a median overall survival of only about 9 to 12 months." (PMID 29895949, 2018). "Previous studies have provided support for the use of EGFR monoclonal antibody for the development of ligand guided nanocarriers for the purpose of tumor imaging or targeted drug delivery." (PMID 30347860, 2018). "The combination of shielding and EGFR retargeting resulted in a fivefold increased gene delivery to the tumor." (PMID 29386504, 2018). "The expression of EGFR in tumor xenograft tissue was determined using the immunoperoxidase technique, revealing intensive positive staining in all tumor cells, being slightly heterogeneous in staining pattern." (PMID 30510514, 2018). "The specificity of the 7A7 mAb to bind EGFR expressed by in vivo tumours was studied in HPV38 and TC-1 (control) tumour samples." (PMID 29552307, 2018). "Several studies have reported a relationship between EGFR signaling and uPAR/integrin signaling with the mechanisms of proliferation, survival and tumor angiogenesis." (PMID 29844873, 2018).
tumor (continued). "Our studies over several years have shown that IGFBP-3 stimulates an oncogenic pathway in which the activation of SphK 1, leading to increased sphingosine-1-phosphate generation, results in the transactivation of EGFR which drives tumor proliferation." (PMID 29623068, 2018). "In contrast, left-sided tumours more often show chromosomal instability and amplification of the epidermal growth factor receptor (EGFR) or human epidermal growth factor receptor 2 and epiregulin tends to be overexpressed." (PMID 29298682, 2018). "When the tumor volume reached 13.20 ± 2.51 mm3, CA-siRNA(s) against EGFR-1(50 nM) or EGFR-2 (50 nM) were given intravenously into the tail vein of mice at 3 days with a total of two injections." (PMID 29861465, 2018). "Among these, EGFR gene amplification was detected in 27/59 (14.8% of the whole study material) tumours and HER2 gene amplification in 24/25 (13.1% of the whole study material) tumours." (PMID 29046940, 2018). "One promising target is the epidermal growth factor receptor (EGFR), which is overexpressed in the majority of HNSCC and is associated to tumor progression and resistance to treatment." (PMID 30345256, 2018). "This option is suggested to be beneficial because of the potential tumor heterogeneity at the time of EGFR TKI resistance." (PMID 29371589, 2018). "Frequently EGFR gene is mutated and overexpressed in head, lung, neck, colon, pancreatic, brain and breast cancers especially in TNBC by stimulating the tumor progression." (PMID 30408068, 2018). "The trimerbody rapidly accumulates in EGFR-positive tumors and exhibits anti-tumor activity similar to IgG-based 4-1BB-agonistic mAbs." (PMID 30442944, 2018). "Inhibition of EGFR phosphorylation by erlotinib (Fig EV1D) induced tumor stasis indicated by significantly reduced tumor number, tumor size, and ALP serum levels, when compared to vehicle‐treated controls." (PMID 30361264, 2018). "Several parallel studies showed that GPRC5A exerts its tumor suppressive effect by regulating the NF-κB and EGFR/STAT3 signaling pathways." (PMID 30417009, 2018). "Higher amount of PTX accumulation of INP in tumor was observed due to longer circulation of PEGylated nanoparticle without phagocytosis action and enhanced permeability as well as anti-EGFR protein specifically bounded with EGFR receptor expressed by TNBC." (PMID 30408068, 2018). "When human FcRn transgenic tumor-bearing mice were treated with either an anti-EGFR antibody or an anti-VEGF antibody containing the M428L/N434S mutations, an increased reduction in tumor burden was observed compared with IgG1 treated animals." (PMID 28986820, 2018). "In previous studies, we defined the comprehensive downstream changes upon inhibition of oncogenic EGFR/ErbB2 in EGFR/ErbB2-addicted tumor models and identified a very select number of genes altered as early as 6 hours following EGFR/ErbB2 blockade." (PMID 29861842, 2018). "An EGFR-derived network has been shown to play an oncogenic role in modulating tumor behavior in various cancers such that EGFR has been considered an effective target for anticancer therapies in certain clinical settings." (PMID 30449278, 2018). "In the A431 EGFR+ tumor model, intratumoral application of HAdV5HVR7 thus led to a tumor-to-liver ratio of 50, which was strongly increased to about 7200 by EGFR targeting and inhibition of the CAR uptake pathway, representing a 140-fold gain in specificity." (PMID 29386504, 2018). "Tumor Microarrays were successfully stained for p-ER, EGFR, p-ERK1/2, p-mTOR, and IGF1R, and scored by a breast pathologist." (PMID 29486734, 2018). "Using Ab-sensitive TUBO (HER2/neu+) and Ab-resistant EGFR-transduced B16 mouse tumor models, they found increased production of type I IFNs in the Ab-sensitive tumor model, in contrast to the Ab-resistant tumor model." (PMID 30533489, 2018).
tumor (continued). "Through its MGMT targeting arm, it can induce S-benzylation and down-regulation of MGMT and potentiation of TMZ in tumour cells co-expressing EGFR and MGMT." (PMID 30416678, 2018). "We found that EGFR expression was reduced in ZJU-1127 tumor xenografts relative to ZJU-0725 and the original tumors." (PMID 30140169, 2018). "A cohort of these so-called xenopatients showed amplification of HER2, particularly in RAS wild-type tumours, suggesting enrichment in this cohort, which showed high and sustained sensitivity to combination EGFR and HER2 inhibition." (PMID 29254887, 2018). "In one mouse with HSC-2 xenograft tumor, four i.v. doses of 30 mg/kg anti-EGFR DAR = 8 MMAU ADC were given with one week intervals." (PMID 31544867, 2018). "The functionalization of the PEG chains with monoclonal antibody cetuximab was also tested for active targeting of epidermal growth factor receptor- (EGFR-)positive tumor." (PMID 30515065, 2018). "Some factors clearly influenced the rate of engraftment: squamous histology, poor differentiation and larger tumor size favored engraftment; importantly, the engraftment was preferential for KRAS-mutated tumors, compared to EGFR-mutated tumors." (PMID 30060526, 2018). "We show that EGFR deletion/inhibition results in reduced tumor formation in H2‐c‐fosLTR mice by directly inhibiting the proliferation of cancer‐initiating osteoblastic cells by a mechanism involving RSK2/CREB‐dependent c‐Fos expression." (PMID 30361264, 2018). "Specifically, Kappa coefficient for EGFR genotyping by using tumor tissue sample and BALF EV DNA was 1.0 (p < 0.01), which was higher than that for EGFR genotyping by using tumor tissue sample and BALF ctDNA (kappa = 0.705)." (PMID 29374476, 2018). "The transferrin (TfR) and epidermal growth factor receptors (EGFR) are known to be overexpressed on the surface of a wide variety of tumor cells." (PMID 29315261, 2018). "In a first step, we estimated EGFR surface expression levels of tumor cells by flow-cytometry on the surface of different tumor cell lines using a commercial anti-EGFR mAb and the fluorescence-based QIFIKIT®." (PMID 29876011, 2018). "EGFR expression is known to activate a cascade of multiple signaling pathways that enable tumor growth process." (PMID 29719621, 2018). "We have also shown that a number of cytokines and chemokines are likely to be upregulated within the tumor microenvironment due to complex interactions between tumor and stromal cells that involve different signaling pathways including the EGFR." (PMID 29707128, 2018). "The detected tumor markers mainly included epithelial cell adhesion molecule (EpCAM), cytokeratin, and epidermal growth factor receptor (EGFR)." (PMID 30192876, 2018). "Alterations in EGFR gene were found in 40% of tumor tissues, alterations in AR gene were detected in 16% of tumors as assessed using the dataset from the MSKCC Prostate cBioportal Database." (PMID 30134822, 2018). "MoAbs are a very promising class of tumor-targeting agents due to their high specificity for molecular targets such as EGFR and EGFRvIII and the ligands EGF and VEGF." (PMID 29914561, 2018). "The bivalent α-EGFR-EGFR TM is able to bind to all tested tumor cell lines although the percentage of bound target cells varies in dependence on the EGFR expression level." (PMID 29876011, 2018). "In our research, we found that NDRG1 plays an important role in mediating the anti-tumor effects of DpdtC in HER2-overexpressed cancer cells through inhibiting the formation of HER2/EGFR heterodimer." (PMID 29467385, 2018). "As well, ST6Gal-I-mediated EGFR sialylation protected tumor cells against gefitinib-induced cell death." (PMID 29402301, 2018). "To mirror concentrations of tumor-derived fragments commonly encountered in cell-free DNA, we introduced gain of an EGFR haplotype at frequencies of 100, 10, 1, 0.1, and 0.01%." (PMID 29590101, 2018).